HK2 (hexokinase 2)
Diseases named in the same sentence as HK2 in open-access papers (continued):
Sharing a sentence is not in itself a finding about the gene and the disease.
colorectal cancer (continued). "Furthermore, FTO and ALKBH5 regulate HK2 in an m6A-dependent manner and regulate colorectal cancer cell proliferation through the HK2-mediated FOXO pathway." (PMID 39175477, 2024). "In colorectal cancer, gallbladder cancer, and acute myeloid leukemia, HK2 may accelerate cancer proliferation and DNA damage repair." (PMID 37524692, 2023). "By blocking the JAK2/STAT3 signaling pathway, ATL I also decreases the proliferation and causes apoptosis of human colorectal cancer cells HCT116 and SW480, slows glycolysis in CRC cells by reducing HK2 expression, and inhibits tumor growth in xenograft colorectal cancer mice." (PMID 37241729, 2023). "A previously published study also revealed that CD276 may regulate glucose metabolism and chemotherapy resistance by controlling the expression of hexokinase 2 (HK2) in colorectal cancer cells." (PMID 36717836, 2023). "LncRNA C1QTNF1 could sponge miR-484 and consequently increase HK2 expression, promoting colorectal cancer cell proliferation, migration, and invasion." (PMID 36072431, 2022). "Previous studies have shown that LH2 could activate the STAT3 signaling to upregulate the HK2 expression in the colorectal cancer cells, thus mediating glycolysis." (PMID 35559258, 2022). "In addition, HK2 was upregulated in colorectal cancer tissues and positively correlated with lncSLCC1 expression and patient survival." (PMID 33602893, 2021). "For instance, Polo‐like kinase 3 (PLK3) could inhibit glucose metabolism by targeting HSP90/STAT3/HK2 signalling, indicating it may serve as a potential therapeutic target in colorectal cancer." (PMID 34423480, 2021). "HK2 silencing can inhibit the growth of colorectal cancer cells." (PMID 34217310, 2021). "In combination with decreased p-PDH expression, HK2 overexpression may represent a marker of unfavorable prognosis, tumor aggressiveness, and recurrence in patients with colorectal cancer." (PMID 30967137, 2019). "In addition, the total colorectal cancer cell burden was determined by qPCR using human-specific HK2 primers." (PMID 30674873, 2019). "However, we have previously demonstrated a decrease in the expression of HK1 and HK2 in majority of colorectal cancer samples." (PMID 30967137, 2019). "Among the five cancer cells, human colorectal cancer SW480 showed the highest HK2 expression level." (PMID 28427443, 2017). "Both colorectal cancer and melanoma cells are more sensitive to HK1 and HK2 deficiency." (PMID 28105937, 2016). "Interestingly, LH2 is a novel regulator to promote the aerobic glycolysis and tumor progression in the colorectal cancer by upregulating hexokinase 2, as LH2 is regulated by HIF-1α, which may mediate the aerobic glycolysis." (PMID 35559258, 2022). "Analysis of The Cancer Genome Atlas (TCGA) datasets revealed a positive correlation between MED15 expression and the expression of HIF target genes, including ENO1, HK2, and VEGFA, in renal and colorectal cancers." (PMID 39947475, 2025). "In colorectal cancer, METTL3 has been shown to have an oncogenic role by stabilizing HK2 and SLC1A2 mRNA via the IGF2BPs axis, regulating glycolytic metabolism and cell proliferation." (PMID 40746529, 2025). "For instance, in colorectal cancer (CRC), B7-H3 enhances glucose uptake and lactate production by upregulating hexokinase 2 (HK2), a critical mediator of B7-H3-induced chemoresistance in CRC cells." (PMID 40658684, 2025). "The results showed that Tec downregulated the protein expression of PKM2, HK2, LDHA and GLUT1, which means that Tec is involved in blocking glycolysis in colorectal cancer cells Fig. (1B)." (PMID 38243936, 2024). "In colorectal cancer cells, METTL3 directly acts on HK2 and GLUT1 mRNA, and the stability of HK2 and GLUT1 mRNA modified by m6A increases." (PMID 37582735, 2023). "CPNE1 is able to regulate glycolysis, and promote colorectal cancer cell growth and drug resistance through AKT-GLUT1/HK2 pathway." (PMID 37077419, 2023).
colorectal cancer (continued). "This promotes the expression of HK2 and GLUT1, and improve the glycolysis and proliferation of colorectal cancer cells." (PMID 37582735, 2023). "In colorectal cancer, CPNE1 increased aerobic glycolysis via regulating AKT-GLUT1/HK2 pathway, and contributed to chemoresistance." (PMID 37077419, 2023). "METTL3 stabilizes GLUT1 and HK2 mRNA in colorectal cancer by directly interacting with the 3′ UTR mRNA of GLUT1 and the 5'/3′-UTRs mRNA of HK2." (PMID 35186927, 2022). "METTL3 stabilizes HK2 and SLC2A1 (GLUT1) expression in colorectal cancer and m6A-dependent glycolysis enhances colorectal cancer progression." (PMID 36249071, 2022). "In colorectal cancer, PLK3 inhibits glucose metabolism by targeting HSP90/STAT3/HK2 signal transduction." (PMID 34217310, 2021). "METTL3 stabilized the expressions of HK2 (HGNC:4923) and SLC2A1 (HGNC:11005) in CRC through a m6A-IGF2BP2/3-dependent mechanism to regulate glycolytic pathways and promote colorectal cancer progression." (PMID 35087827, 2021). "Catalytic enzymes, such as hexokinase 2 (HK2), pyruvate kinase M2 (PKM2), lactate dehydrogenase A (LDHA), and GLUT-1, are markedly inhibited by NDRG2 expression in colorectal cancer cells and patients." (PMID 34685629, 2021). "Mechanically, HK2 and GLUT1 were found to be regulated by m6A modification and participate in glycolysis activation in colorectal cancer." (PMID 32245489, 2020). "We demonstrated that miR-1 suppressed aerobic glycolysis while Smad3 promoted it via its downstream effecter HIF-1α and glycolytic enzymes, including HK2, MCT4, in colorectal cancer." (PMID 28471448, 2017). "In order to silence the expression of HK mRNA in colorectal cancer and melanoma cells, the cell lines were transfected with HK1, HK2, and HK3 shRNA (three shRNAs per each gene: sh#1, sh#2, and sh#3)." (PMID 28105937, 2016). "Consistent with the target molecules inhibited in NDRG2-overexpressing colorectal cancer cells, the expression of GLUT1, glycolytic pathway-related enzymes HK2, PKM2 and LDHA increased significantly in NDRG2-knockdown Caco-2, HT-29 and HCT116 cells." (PMID 26317652, 2015). "To verify the relationship between NDRG2 and the target molecules in vivo, we also investigated the expression of NDRG2 and c-Myc, β-catenin, GLUT1, HK2, PKM2, LDHA, ASCT2, GLS1 in tissues from clinical colorectal carcinomas samples." (PMID 26317652, 2015). "In patients with colorectal cancer (CRC), METTL3 enhances the stability of hexokinase 2 (HK2) and glucose transporter GLUT1 mRNAs by interacting with their 3′UTR regions, with the stability of HK2 and GLUT1 being mediated by IGF2BP2 and IGF2BP3, respectively." (PMID 40428320, 2025). "The PI3K/Akt signaling axis is significantly activated in colorectal cancer, and enhanced PI3K/Akt signaling not only directly activates GLUT1/4, HK2, and PFKFB3/4 but also coordinates glucose metabolism, nucleotide metabolism, and amino acid synthesis via activation of the mTOR pathway." (PMID 41488637, 2025). "Worenine, an alkaloid from Coptis chinensis Franch., targets HIF1α to decrease glycolytic activity and downregulate the expression of glycolytic enzymes (PFK-L, HK2, and PKM2), thereby inhibiting colorectal cancer cell growth, proliferation, and cell cycle progression." (PMID 39330497, 2024). "After c-MYC is reduced, the expression of HK2, PFKM, PKM2 and LDHA in colon cancer cells is reduced, glycolysis is inhibited, and intracellular ATP is reduced, resulting in endoplasmic reticulum stress and immunogenic cell death in colorectal cancer cells." (PMID 39609317, 2024). "Moreover, in colorectal cancer, METTL3 targets genes such as SOX2, HK2, SLC2A1, and CBX8, inducing metastasis-related processes and activating the glycolysis pathway and cellular stemness." (PMID 38966069, 2024). "Moreover, N6-methyladenosine modifications of HK2 and GLUT1 regulate glycolysis to enhance colorectal cancer progression." (PMID 37428395, 2023).
colorectal cancer (continued). "Similarly, IGF2BP2 stabilizes the HK2 and SLC2A1 mRNAs, and accelerates glycolytic metabolism and cell proliferation in colorectal cancer." (PMID 35299748, 2022). "Hexokinase 2 (HK2) and pyruvate kinase M2 (PKM2), the rate-limiting enzymes of cellular glycolysis, are remarkably upregulated in glioma, colorectal cancer, and liver cancer, promoting glycolysis and have been generally accepted as key factors in the reprogramming of glucose metabolism." (PMID 36064939, 2022). "In colorectal cancer, METTL3 expression was found to be much higher in patients with higher FDG uptake, promoting cancer progression, which depends on cell glycolytic metabolism, by stabilizing HK2 and GLUT1 expression in an m6A-IGF2BP2/3-dependent manner." (PMID 34996469, 2022). "In addition to lipogenesis and adipogenesis, METTL3 was found to regulate glucose metabolism in colorectal cancer, as METTL3-mediated m6A promoted the mRNA stability of Hk2 and Glut1 in an m6A and IGF2BP2/3-dependent manner." (PMID 35350378, 2022). "Next, to analyze if KCNQ1OT1 functions as an oncogenic lncRNA in colorectal cancer by regulating HK2 expression, we transfected KCNQ1OT1-knockdown HCT116 cells with the pcDNA3.1-HK2 plasmid and obtained HK2 levels that were similar to parental HCT116 cells as analyzed by western blotting." (PMID 32564010, 2020). "This study suggests that PLK3 inhibits glucose metabolism by targeting HSP90/STAT3/HK2 signaling and PLK3 may serve as a potential therapeutic target in colorectal cancer." (PMID 31655629, 2019). "We observed increased expression of HK1 in colorectal cancer cells with HK2 gene silencing, but not in melanoma cells." (PMID 28105937, 2016). "Inactivation of HK2 was followed with up-﻿regulation of HK1 expression in colorectal cancer, but not in melanoma cells." (PMID 28105937, 2016). "The expression levels of HK1 and HK2 were not significantly changed in both colorectal cancer and melanoma cells with HK3 knockdown." (PMID 28105937, 2016). "The purpose of the present study was to investigate the effect of silencing of hexokinase genes (HK1, HK2, and HK3) in colorectal cancer (HT-29, SW 480, HCT-15, RKO, and HCT 116) and melanoma (MDA-MB-435S and SK-MEL-28) cell lines using short hairpin RNA (shRNA) lentiviral vectors." (PMID 28105937, 2016). "In our results, it was revealed that Tec treatment could effectively inhibit the proliferation of HCT116 colorectal tumor cells, and the expression of PKM2, HK2, LDHA and GLUT1 protein decreased, suggesting that glycolysis might be the promising target of Tec for anti-colorectal cancer therapy." (PMID 38243936, 2024). "METTL3 has been found to guarantee the stability of hexokinase 2 (HK2) and solute carrier family 2 member 1 (SLC2A1) via an m6A-insulin-like growth factor 2 mRNA-binding protein 2 (IGF2BP2)/3-dependent pathway, contributing to the tumorigenesis of colorectal cancer (CRC)." (PMID 35804965, 2022).
prostate carcinoma (84 papers, 2002 to 2026). A carcinoma that arises from epithelial cells of the prostate gland. "Recent studies have suggested that silencing HK2, a glycolytic enzyme often upregulated in cancer cells, was associated with increased apoptosis in prostate cancer models." (PMID 34944758, 2021). "In agreement with these cell experiments, the histopathological analysis showed that in prostate cancer patient samples, upregulation of both HK2 and SENP1 is associated with poor prognosis and poor response to docetaxel-based chemotherapy." (PMID 33753739, 2021). "Because the binding of HK2 to mitochondria increases glycolysis, it is likely that Akt not only increases HK2 expression but also increases its activity in PTEN-deficient prostate cancer." (PMID 29687779, 2018). "HK2 knockdown in Pten-deficient prostate cancer cells in mice markedly inhibited their tumor growth and overcame their resistance to etoposide." (PMID 29687779, 2018). "Here we show that silencing HK2 in human PTEN-deficient prostate tumors and deleting HK2 in a mouse model of Pten-deficient prostate cancer inhibits cancer development in both cytostatic and cytotoxic manners." (PMID 29687779, 2018). "We also found that in PTEN-deficient prostate cancer, HK2 is induced because of Akt activation to increase glycolysis." (PMID 29687779, 2018). "We found that a high level of glycolysis in PTEN-deficient prostate cancer cells is partially dependent on the ability of Akt to elevate HK2 expression." (PMID 29687779, 2018). "When combined, the odds ratio for prostate cancer for patients with high hK2 levels and the variant T-allele of rs198977 was 3.77 (95% CI: 1.94-7.32, p < 0.0001), compared to patients with low hK2 levels and the C-allele." (PMID 25279276, 2014). "The human kallikrein-2 (hK2) protein and two single nucleotide polymorphism (SNPs) (rs2664155, rs198977) of the gene are associated with prostate cancer risk." (PMID 25279276, 2014). "The KLK2 SNP rs198977 was found to be positively associated with hK2 levels and shown to predict prostate cancer at the time of repeat prostate biopsy." (PMID 25279276, 2014). "Among pre-screened men undergoing a repeat biopsy, we have found an association between the KLK2 SNP rs198977 as well as serum hK2 levels and prostate cancer." (PMID 25279276, 2014). "The KLK2 SNP rs198977 was positively associated with hK2 levels and predicts prostate cancer at the time of repeat prostate biopsy." (PMID 25279276, 2014). "We also showed that single nucleotide polymorphisms (SNPs) of the KLK2 gene, which encodes for the hK2 protein have been shown to be associated with prostate cancer." (PMID 25279276, 2014). "We and others have shown that a serine protease, human kallikrein-2 (hK2), was positively associated with prostate cancer." (PMID 25279276, 2014). "Increased concentrations of HK2 in the blood are associated with an aggressive type of prostate cancer, and HK2 typically is overexpressed in prostate cancer tissue." (PMID 24213111, 2011). "HK2 levels are high in prostate cancer, especially in association with poor prognosis." (PMID 33753739, 2021).
prostate carcinoma (continued). "HK2 deficiency also overcomes the chemoresistance of PTEN-deficient prostate cancer cells." (PMID 29687779, 2018). "Indeed, HK2 deficiency in mouse models of Pten-deficient prostate cancer elicited a marked inhibition of tumor development and extended lifespan." (PMID 29687779, 2018). "Additionally, serum hK2 level was associated with prostate cancer (OR = 2.03, 95% CI: 1.4-2.99, p = 0.002)." (PMID 25279276, 2014). "Previous evidence has shown that PSA measures, including total and free PSA, as well as hK2, were significant predictors of prostate cancer diagnosed ≥20 years after blood collection." (PMID 40844611, 2025). "One study shows that HectH9 E3 ligase can play a key role in glucose metabolism regulation in prostate cancer via its control on the ubiquitination of hexokinase 2 (HK2), and the HectH9-HK2 pathway can regulate the maintenance of PC3-derived PCSCs." (PMID 40044646, 2025). "Regulating the signaling pathway AR‐Akt‐HK2 was the primary mechanism by which wogonin's anticancer effect on prostate cancer was mediated." (PMID 41164269, 2025). "QUESTION: Can hK2 expression be leveraged as a prostate cancer imaging and therapeutic target in humans?" (PMID 38782459, 2024). "IMPLICATIONS FOR PATIENT CARE: This study highlights the feasibility of hK2 as a prostate cancer target and supports continued investigation of h11B6 or other hK2-targeting agents in the treatment of mCRPC." (PMID 38782459, 2024). "Through characterization of h11B6 biodistribution in human participants, this study further adds to previous preclinical prostate cancer studies by validating the expression of hK2 in mCRPC, providing data to support the use of h11B6 in a clinical setting." (PMID 38782459, 2024). "It has been shown that higher hK2 expression correlates with increased cell proliferation and lower apoptosis in castration-resistant prostate cancer specimens, thereby modulating the growth of castration-resistant disease." (PMID 38782459, 2024). "Increased AR signaling activity has demonstrated increased hK2 expression but decreased PSMA expression in multiple prostate cancer models." (PMID 38782459, 2024). "Our previous work has shown a synergistic tumoricidal efficacy of combining the hexokinase (HK) inhibitor 2‐deoxyglucose (2‐DG) and the autophagy inhibitor chloroquine (CQ) through intraperitoneal injections on HK2‐addicted prostate cancers in animal models." (PMID 38294142, 2024). "Our previous work has shown a synergistic tumoricidal action of the hexokinase (HK) inhibitor 2-deoxyglucose (2-DG) and the autophagy inhibitor chloroquine (CQ) on HK2-addicted prostate cancers in animal models through intraperitoneal injections." (PMID 36993275, 2023). "In prostate cancer, a few regulators, such as HK2 and SLC2A3, were indicated to participate in the regulation of PCa progression." (PMID 35242214, 2022). "The switch from HK2 to HK3 mediated glucose conversion in cancer cells is also interesting in this respect, since HK2 is important in mediating the Warburg effect in prostate cancer." (PMID 36282866, 2022). "Epigenetic repression of EAF2-HIF1α by EZH2 has been shown to foster metabolic reprogramming in glioblastoma and to promote aerobic glycolysis by upregulating HK2 in prostate cancer." (PMID 35888776, 2022). "Up-regulation of circ-ZNF609 is found to increase the radioresistance of prostate cancer cells by sponging miR-501-3p leading to HK2 up-regulation and enhancing glycolysis." (PMID 36142355, 2022). "Our studies demonstrated that Golgi membrane protein 1 (GOLM1) and hexokinase-2 (HK2) were directly controlled by miR-143-3p and miR-145-5p in prostate cancer and renal cell carcinoma, respectively." (PMID 35327465, 2022).